IL6 (interleukin 6)
Diseases named in the same sentence as IL6 in open-access papers (continued):
Sharing a sentence is not in itself a finding about the gene and the disease.
breast cancer (continued). "Breast cancer cell lines T47D and MCF7 were exposed to IL-6, the expression of PIM1 was examined by quantitative real-time PCR (qRT-PCR) and western blot." (PMID 30989585, 2019). "We report, in this study, its novel tumor suppressive roles via CSC control on breast cancer cells and the STAT3/IL6 axis and NFkB signaling that drive this functionality." (PMID 31709178, 2019). "In the present study, our data identified that PIM1 was induced by IL-6 and participated in IL-6-mediated EMT and stemness in breast cancer." (PMID 30989585, 2019). "The present study clearly showed that the expression of inflammatory factors including IL-1, IL-6, IL-17, TNF-α, TGF-β, NF-κB and RONS in HPV-positive breast cancer patients were higher than HPV-negative breast cancer patients and healthy controls." (PMID 30642295, 2019). "A recent study demonstrated that high levels of serum IL-6 and fibroblast growth factor-2 (FGF-2) contributed to the resistance of anti-VEGF therapy in obese breast cancer patients and mouse models." (PMID 31500658, 2019). "Elevated levels of Serpine1, IL-6, and SNAI2 correlate with the pro-metastatic phenotype of breast cancer cells induced by obASCs in vitro and the increase in metastatic lesions in the lungs of mice with TNBC tumors grown with obASCs." (PMID 31118047, 2019). "Although the expression of MMP-8 is detrimental to breast cancer cells, MMP-8 upregulates pro-tumor cytokines, IL-6 and IL-8, in a self-reinforcing loop manner." (PMID 31010242, 2019). "IL-6 is also strongly induced in adipocytes and tumor-infiltrated myeloid cells after anti-VEGF treatment on overweight breast cancer patients." (PMID 31474975, 2019). "In view of the well-documented functions of the IL-6/STAT3 signaling pathway in tumor growth promotion, we examined its role in macrophage-mediated breast cancer cell proliferation." (PMID 30736340, 2019). "The role of IL‐6 and TNF‐α in the adhesion, migration, and apoptosis of breast cancer cells has attracted more and more attention." (PMID 31762993, 2019). "Since MTF down-regulated Vimentin and SNAIL levels in mesenchymal breast cancer primary cells, a model of EMT induction using IL-6, which is a well-known EMT inducer in several types of tumors including breast cancer, was established." (PMID 31337349, 2019). "Interaction between macrophages and ERα+ breast cancer cells in a proinflammatory microenvironment favors expression of TNF-α and IL-6." (PMID 30736340, 2019). "To reduce the probability of saturating the cell’s capacity to produce IL-6 and to better assess a possible synergistic interaction between OSM and IL-1β in breast cancer cells, we decreased the amount of OSM used in the experiments from 25 ng/mL to 10 ng/mL." (PMID 31007849, 2019). "Previous studies have reported that IL-6 induced CD44+ cells with stem-like and EMT properties in breast cancer." (PMID 30989585, 2019). "Then, human bone samples from the femoral heads of patients undergoing total hip replacement or proximal femur replacement with breast cancer metastases to the bone were stained for RUNX2, OCN, IL-6, and alpha-SMA using multi-plex immunofluorescence." (PMID 30813947, 2019). "In breast cancer cells, epithelial-to-mesenchymal (EMT) and stem-cell-like phenotypes were attenuated by either anti-IL-6 or anti-IL-1β antibody treatment." (PMID 31231372, 2019). "Our studies with breast cancer patients showed that high serum levels of OSM and IL-6 are correlated, and OSM has been shown to induce IL-6 expression in smooth muscle cells, osteoblasts, and astroglioma cells." (PMID 31007849, 2019). "We also demonstrate that co-treatment of ER− breast cancer cells with both OSM and IL-1β leads to a synergistic increase in IL-6 secretion." (PMID 31007849, 2019). "OSM promoted IL-6 secretion approximately 5-fold in MDA-MB-468 cells, ∼4-fold in MDA-MB-231 cells, and ∼4-fold in 4T1.2 mouse mammary carcinoma cells." (PMID 31007849, 2019).
breast cancer (continued). "The present study confirmed the potential role in the progression of breast cancer of RANTES and IL-6." (PMID 29707128, 2018). "More importantly, we recently reported that recombinant IL-6 cooperates with other factors, such as recombinant VEGFA, in sustaining breast cancer cell migration." (PMID 29707128, 2018). "In particular, in the presence of breast cancer cells, reprogramming CAA increase expression of miR-5112, which suppresses the translation of Cpeb1, a negative regulator of interleukin (IL)-6." (PMID 30200265, 2018). "We found IL-6 and its downstream target phosphorylated STAT3 to be significantly activated in both breast cancer cells after co-culture." (PMID 29891854, 2018). "Nuclear PY-YAP and IL-6 decreased in MDA-MB-231 and MDA-MB-468 breast cancer cells incubated in the presence of RA plus cerivastatin." (PMID 29728589, 2018). "Additionally, TAMs play a critical role in the tumor microenvironment by secreting second messengers such as IL-8 or IL-6 via NF-κB activation, thus promoting the tumor microenvironment and regulating angiogenesis, which, in turn, correlates with poor outcome and malignant features in breast cancer." (PMID 30103404, 2018). "In this present study, aspirin suppressed MCP-1, PAI-1, and IL-6 production by 4T1 cells cultured in fresh medium and RAW-CM, suggesting to inhibit proliferation and migration of breast cancer cells." (PMID 30034291, 2018). "Taken together, we determined that IL-6, CCL2, MMP9, MMP2, and CHOP expression are all inversely correlated with IGF-1R expression in human breast cancer." (PMID 30458886, 2018). "Increased expression of IL-6 resulted in phosphorylation of STAT3 and its nuclear accumulation in co-culture breast cancer cell." (PMID 29891854, 2018). "Cross-talk between AhR and NF-KB pathways has also been implicated in the regulation of AhR-mediated gene transcription such as IL6 and IL8 in breast cancers." (PMID 29320557, 2018). "In breast cancer, AHR activation by TCDD promotes interleukin 6 (IL-6) induction in the presence of an inflammatory signal by directly binding with the IL-6 promoter." (PMID 29301348, 2018). "We show here that cerivastatin can reverse the effect of RA in MDA-MB-231 breast cancer cells by decreasing nuclear PY-YAP localization, IL-6 expression, and the invasive phenotype of these cells." (PMID 29728589, 2018). "Further investigation revealed that adipocyte-derived IL-6 and leptin promote PLOD2 expression, thus facilitating breast cancer metastasis." (PMID 30563531, 2018). "To assess the effects of the simultaneous expression of IL-6 and RANTES on breast cancer cell proliferation, we analyzed the anchorage-dependent and -independent growth of stable transfectants." (PMID 29707128, 2018). "IL-6 mainly promotes the expression of multiple genes through STAT3, thus regulating breast cancer drug resistance." (PMID 30175384, 2018). "Our study reveals that adipocyte-derived IL-6 and leptin promote PLOD2 expression by activating the JAK/STAT3 and PI3K/AKT signaling pathways, thus promoting breast cancer metastasis." (PMID 30563531, 2018). "In order to assess the effects of the simultaneous overexpression of RANTES and IL-6 on the tumor cell phenotype, we overexpressed both proteins in MCF-7 and MDA-MB-231 human breast cancer cell lines." (PMID 29707128, 2018). "Tumor-associated fibroblasts induce hepcidin expression via paracrine IL-6-BMP signaling, and this induction facilitates breast cancer cells growth." (PMID 30591630, 2018). "In MDA-MB-468 breast cancer cells, the presence of exogenous RA (5 μM) for 48 h decreased nuclear Src activity, nuclear PY-YAP and downregulated IL-6." (PMID 29728589, 2018). "It is highly efficacious in ameliorating several chronic diseases such as asthma, diabetes, cancers of breast, cervical, stomach, etc. via the inhibition of STAT3, NF-κB, PGE2, IL-6, TNF-α, etc.." (PMID 29370858, 2018).
breast cancer (continued). "In this regard, we and other groups have previously demonstrated that IL-6 is able to promote the migration and the invasion of both ER-positive and HER2-positive breast cancer cells." (PMID 29707128, 2018). "When RANTES and IL-6 were simultaneously expressed, a more significant increase in the migration of both MCF-7 and MDA-MB-231 cells was observed, as compared to breast cancer cells transfected with RANTES or with IL-6 alone." (PMID 29707128, 2018). "In breast cancer, as in physiological contexts, STAT3 can be activated by cytokine receptors, particularly receptors for interleukin-6 (IL-6) family cytokines, including the OSM receptor, as described in the second phase of involution." (PMID 29875329, 2018). "Indeed, IL-6 could promote EMT process in breast cancer cells." (PMID 30456206, 2018). "Our findings suggest that IL-6-mediated cross-talk between preadipocytes and breast DCIS cells can promote the progression of early stage breast cancer." (PMID 30134951, 2018). "To address the molecular mechanisms through which IL-6 and RANTES promote breast cancer cell migration and invasion, we analyzed their effects on the activation of ERK1/2, AKT and STAT3 signal transduction proteins at different time points." (PMID 29707128, 2018). "Many of the genes regulated have previously been shown to correlate with aggressiveness of breast cancer such as CD24, SOX2, Slug, Twist1, CD-133, N-Cadherin, E-Cadherin, FOXC2, ABCG2, c-Myc, IL8, IL6, and IKKβ (activating NF-κB signaling)." (PMID 29552303, 2018). "Together, our results suggest that matured human adipocytes can enhance the aggressive behaviour of breast cancer cells and induce an EMT-phenotype through paracrine IL-6/STAT3 signalling." (PMID 29891854, 2018). "b Dot hybridization analysis of IL-6 and leptin secretion in 3 T3-L1 preadipocytes, adipocytes and adipocytes cocultured with MDA-MB-468 (MB-468) breast cancer cells." (PMID 30563531, 2018). "In the established MDA-MB-231 metastatic breast cancer cell line, knockdown of endogenous VCAM-1 expression reduced cell proliferation and inhibited IL-6 mediated cell migration, and increased chemosensitivity." (PMID 30175384, 2018). "On the other hand, the IL-6/JAK/STAT3 autocrine activation loop is a critical driver of cancer progression and metastasis in breast cancer." (PMID 30581487, 2018). "MDSCs in breast cancer have also been shown to induce Notch signaling in cancer cells and promote CSC capacity through IL6/STAT3 & Nitric Oxide/Notch cross talk signaling." (PMID 30515368, 2018). "The secretion of IL-6 and leptin was increased in the supernatant of adipocytes cocultured with MDA-MB-231 and MDA-MB-468 breast cancer cells compared with 3 T3-L1 preadipocytes and adipocytes." (PMID 30563531, 2018). "a qRT-PCR analysis of the relative expression levels of IGF-BP1, PAI-1, IL-6, MIF, TIMP-1, TIMP-2 and leptin in adipocytes and adipocytes cocultured with MDA-MB-468 (MB-468) breast cancer cells." (PMID 30563531, 2018). "Further analysis of the METABRIC dataset revealed an increase in IL-6, CCL2, and MMP-9 expression in patients with low IGF-1R, consistent with our mouse tumor model and data in human breast cancer cell lines." (PMID 30458886, 2018). "Moreover, aiming breast cancer cells with IL-6 inhibits proliferation in estrogen receptor (ER) positive cells, however, the main role of IL-6 in breast cancer considers the prognostic use with elevated circulating IL-6 levels being correlated with a poor prognosis in many studies." (PMID 30648081, 2018). "In conclusion, our data suggest that the simultaneous expression of IL-6 and RANTES produces a more aggressive phenotype in breast cancer cells." (PMID 29707128, 2018). "By suppressing the secretion of SASP factors such as IL-6, the MDM2 inhibitors suppressed the ability of senescent human fibroblasts to stimulate breast cancer cell aggressiveness (invasiveness and an EMT)." (PMID 29402901, 2018).
breast cancer (continued). "Together, our results suggest that pharmacological inhibition of IL-6 and leptin as well as the downstream JAK/STAT3 and PI3K/AKT signaling pathways can decrease PLOD2 expression and suppress breast cancer metastasis." (PMID 30563531, 2018). "Further, elevation of MAO-A with 5-azacytidine (5-Aza) modulated IL-6 mediated angiogenesis and invasive signatures including VEGF, MMPs and EMT in hypoxic breast cancer." (PMID 29695771, 2018). "It is well-known that IL-6, CCL2, and MMP9 expression are increased in TNBC compared to ER+/PR+ breast cancer." (PMID 30458886, 2018). "We demonstrated that IL-6 secreted from preadipocytes is a crucial molecule in the cross-talk between preadipocytes and DCIS cells in the early stage of breast cancer development." (PMID 30134951, 2018). "Taken together, these data show that breast cancer-derived exosomes induce the gp130–STAT3 pathway, resulting in IL-6 secretion by BMDMs." (PMID 29867925, 2018). "Previous analysis of the human patient gene expression datasets revealed IL-6, CCL2, and MMP9 expression are upregulated in TNBC compared to ER+/PR+ breast cancer." (PMID 30458886, 2018). "Our data demonstrates that human adipocytes can enhance the proliferation, invasion and migration characteristics of breast cancer cells and induce an EMT phenotype through paracrine IL-6/STAT3 signalling." (PMID 29891854, 2018). "In this study, we confirmed the efficacy of target therapy against IL-6 signaling and STAT3 phosphorylation in the treatment of breast cancer." (PMID 30083161, 2018). "Higher expression levels of IL-6 have also been observed in various human cancer tissues, and IL-6 is known to induce EMT through STAT3 activation in human breast cancer cells." (PMID 29969465, 2018). "In breast cancer models, TEXs adopt TGF-β and IL-6 pathway to differentiate BMDCs towards MDSCs phenotype." (PMID 28642882, 2017). "Several important molecular targets were identified, such as vimentin (VIM), NFκB, β-tubulin, uPA (PLAU), interleukin-6 (IL-6), STAT3 or ESR, and more recently in vivo mouse models have confirmed WA efficacy in mammary tumors and BC xenografts." (PMID 28467815, 2017). "IL-6 stimulated SOCS3 suppression and thus induced long-term activation of the JAK/STAT signaling pathway in breast cancer MDSCs." (PMID 29326716, 2017). "In contrast to untransformed cells, the breast cancer cells had a very low expression of the cytokines, at both at neutral (IL6: 0.004±0.002; IL8: 0.044±0.005) and acidic (IL6: 0.004±0.001; IL8: 0.049±0.007) pH values." (PMID 28903357, 2017). "Among these factors, IL-6 and CXCL12 have been reported to promote cell growth in prostate and breast cancer respectively." (PMID 28258248, 2017). "Numerous studies showed that IL-6 and STAT are involved in tumor progression and metastasis in various types of cancer, including breast cancer, renal cancer, prostate cancer, and lung cancer." (PMID 29100297, 2017). "In conclusion, our data demonstrate that PsA-D is able to significantly decrease expression of the cytokines IL-6 and MCP-1 after stimulation with pre-conditioned medium in monocytes and breast cancer cells, respectively." (PMID 28832545, 2017). "IL-6, a major cytokine present in the tumour microenvironment, can induce EMT and promote metastasis through the STAT3 signalling pathway in breast cancer, head and neck cancer and pancreatic cancer." (PMID 28198361, 2017). "In this study, we evaluated the correlation between tumor-derived IL-6 and MDSC infiltration in 253 paraffin-embedded primary breast tissues and 20 fresh breast cancer tissues." (PMID 29326716, 2017). "For example, elevated expression of IL6 and other chemoresistance‐related genes accompanies the EMT in a mouse breast cancer model." (PMID 28618162, 2017). "We have shown here that fibroblast SCM is highly enriched in IL6 and IL8 and that these cytokines were capable of inducing an EMT-like program in MCF-7, another luminal breast cancer cell line." (PMID 28472950, 2017).
breast cancer (continued). "In conclusion, both IL-6 and EGFR promote breast cancer through STAT3 abnormal activation and predict a poor prognosis." (PMID 27861147, 2017). "This study demonstrates an association between elevated pre-chemotherapy peripheral blood biomarkers of aging (IL-6 and D-dimer) and reduced RDI in women with stage I–III breast cancer receiving neoadjuvant or adjuvant chemotherapy." (PMID 28851415, 2017). "Shp2 is essential for the IL-6-induced EMT of breast cancer cells, and both the phosphatase activity of Shp2 and its tyrosine phosphorylation, are necessary for the EMT triggered by IL-6." (PMID 28208810, 2017). "Breast cancer cells that constitutively expressed Twist, a EMT regulator and direct transcriptional repressor of E-cadherin, exhibited aberrant IL-6 production and STAT3 activation." (PMID 28186964, 2017). "High levels of both IL-6 and of CCL5 correlate with bad prognosis and an advanced metastatic stage in prostate and breast cancer." (PMID 28477013, 2017). "One of these, IL-6, is a pleiotropic cytokine that enhances the proliferation of cancer cells and, reportedly, plays a central role in EMT in breast cancer." (PMID 28061440, 2017). "High expression of IL6 and IL8 was significantly correlated with poor survival in breast cancer and lung cancer, which is consistent with a previous report." (PMID 28618162, 2017). "IL-6 is a direct regulator of breast CSC self-renewal and IL-6/JAK2/STAT3 pathway is more active in CD44(+)CD24(-/low) breast cancer cells compared with other tumor cell types and its inhibition blocks the growth of xenografts." (PMID 28270211, 2017). "To test this possibility, we evaluated IL-6-mediated STAT3 phosphorylation in both control and PTPRD-silenced breast cancer cells." (PMID 29228728, 2017). "We have previously shown that Syndecan-1 modulates the expression of IL-6, IL-6R in different experimental models of inflammation and in MDA-MB-231 breast cancer cells." (PMID 28270211, 2017). "More recently, a role for IL‐6 in inducing and maintaining EMT was shown in other breast cancer cell lines." (PMID 28599100, 2017). "Pretreatment with extract significantly decreased the levels of IL-8, IL-6, MMP-2 and MMP-9 in the breast cancer cells." (PMID 28264501, 2017). "Therefore, determining the detailed molecular mechanisms that regulate IL-6-dependent recruitment and amplification of MDSCs in breast cancer may help screen for potential therapeutic targets to eradicate MDSCs and reverse MDSCs-mediated immune tolerance in breast cancer patients." (PMID 29326716, 2017). "Based on our previous findings that C10 significantly reduced IL-6 protein levels and STAT3 phosphorylated via TLR3 signaling in other cancers, we also evaluated these in MCF-7 breast cancer cells." (PMID 29371911, 2017). "In MDA-MB-231 breast cancer cells incubated with PsA-D led to a reduction of MCP-1 by 85%, a decrease of TNFα release by 75%, and a decrease of IL-6 by 38%." (PMID 28832545, 2017). "In our previous report, IL-6 was expressed in more aggressive breast cancer cells, including basal-like cells, and TG2 was the upstream molecule that induced IL-6 production in these cells." (PMID 27609180, 2016). "We knocked down C/EBP-β by siRNA treatment, which reduced IL-6 and CXCL9 expression induced by miR-155 inhibition in two breast cancer cell lines." (PMID 26848978, 2016). "The targets of the top luminal miRNAs were activators of EMT (ZEB1, ZEB2) and basal subtype transcription (IL-6, EGFR, STAT3), whereas the targets of the top basal miRNAs were involved in adipogenesis pathways and luminal breast cancer (ERBB2, ERBB3)." (PMID 27845906, 2016). "We further examined IL-6 and CXCL9, as IL-6 is a well-known target whereas the CXCL9 is uncharacterized target of the C/EBP-β in breast cancer." (PMID 26848978, 2016). "We assessed the effect of morphine on the production of IL-6, TNF-α and VEGF-A by macrophages and breast cancer cells grown individually or co-cultured in a transwell." (PMID 27514308, 2016).